CAV1 (caveolin 1)
Diseases named in the same sentence as CAV1 in open-access papers (continued):
Sharing a sentence is not in itself a finding about the gene and the disease.
clear cell renal cell carcinoma (10 papers, 2012 to 2023). "Up-regulation of RhoA/ROCK and Cav-1 expression is considered to be associated with the development and progression of clear cell renal cell carcinoma (ccRCC)." (PMID 26066055, 2015). "miR-204 indirectly inhibits TRPM3-mediated downstream LC3B-related autophagy through Cav-1, thereby inhibiting the progression of clear cell renal cell carcinoma." (PMID 34955837, 2021). "RT-qPCR and western blot analysis were used to screen the cell line with the highest expression of CAV1 among human renal clear-cell adenocarcinoma cell lines 786-O, ACHN, OS-RC-2, and ketr-3." (PMID 32990143, 2020). "Hypoxia and hypoxia-inducible factor 1 have been demonstrated to positively regulate caveolin-1/CAV1 in clear cell renal cell carcinoma." (PMID 29065889, 2017). "Their studies were performed on clear cell renal cell carcinoma tissue sections from 67 patients undergoing radical nephrectomy, using double immunohistochemical staining with specific antibodies against Cav-1 and the EC-specific marker CD34." (PMID 26605130, 2012). "(2015 May) miRNA-target network reveals miR-124as a key miRNA contributing to clear cell renal cell carcinoma aggressive behaviour by targeting CAV1 and FLOT1." (PMID 37219053, 2023). "Literature search has revealed different targets of miR-124 in different tissues and tumor types, such as Foxq1 in nasopharyngeal cancer, CCAAT/enhancer-binding protein-α in macrophages, PTBP1 in neuronal differentiation, and CAV1 and FLOT1 in renal clear cell carcinoma." (PMID 28212569, 2017).
cognitive deficits (10 papers, 2019 to 2025). "Thus, the modulation of the expression of genes involved in the inflammatory response of brain (Cav1, Bdnf) may contribute to alleviation of neuroinflammation and the progression of cognitive disorders." (PMID 35468904, 2022). "We used Cav-1-deficient mice with genetically encoded fluorescent endothelial tight junctions to determine how Cav-1 influences BBB permeability, neuroinflammation, and cognitive impairment following respiratory infection with mouse adapted (MA10) SARS-CoV-2 as a model for COVID-19." (PMID 38335781, 2024). "Clinical neuropathy and cognitive deficits are associated with CGL2 and mutations in seipin (BSCL2), and are rare but not unknown for CGL3 and CGL4 syndromes [associated with caveolin-1 (CAV1) and cavin (RNA polymerase 1 and transcript release factor: PTRF) gene mutations, respectively]." (PMID 30563316, 2019).
hypertriglyceridemia (10 papers, 2008 to 2024). A laboratory test result indicating elevated triglyceride concentration in the blood. "In a simple way these differences between groups suggest a tendency that relates CAV1 variations and hypertriglyceridemia in adult population, where the risk allele is acting as a recessive character." (PMID 29662258, 2017). "In humans, CAV-1 is one of the locis identified associated with inherited lipodystrophy and hypertriglyceridemia." (PMID 20226013, 2010). "Studies performed with Cav1 knockout mice have shown that a reduction of Cav1 expression in the organism reflects in a higher hypertriglyceridemia." (PMID 33800461, 2021). "Decreased CAV-1 gene expression was simultaneously linked to increased triglycerides and decreased lipogenic gene expression among obese subjects, paralleling the observations of hypertriglyceridemia in CAV-1 knockout mice." (PMID 20226013, 2010). "Those obese subjects with decreased sc-CAV-1 had the highest fasting triglyceride concentrations, paralleling, to some extent, the observations of hypertriglyceridemia in CAV-1 knockout mice." (PMID 20226013, 2010).
liver disease (10 papers, 2015 to 2025). "Moreover, the pathophysiological process underling the role of caveolin-1 has been already highlighted by a clinical point of view in studies indicating that indirect markers of portal hypertension are in turn associated with increased HCC occurrence and recurrence." (PMID 32676485, 2020). "It is suggested that the changes of Cav-1 expression and function are related to the occurrence and development of liver disease." (PMID 33558888, 2021). "Cav-1 is rarely found in normal liver tissues, but its expression changes in the state of liver disease." (PMID 33558888, 2021). "Therewith, applying the cell type specific knockout in context of LSEC and other liver cells will be relevant to broaden our understanding on CAV1 in liver disease contexts." (PMID 32029710, 2020). "It is possible that Cav1 may also has different roles depending on the stage of the liver disease as previously findings in lung injury." (PMID 34434195, 2021). "Intriguingly, CAV1 is overexpressed in various liver disease and HCC (but not in non-alcoholic fatty liver disease, own observations), suggesting that its expression may enable diseased hepatocytes to escape from detrimental TGF-β-induced responses." (PMID 32082178, 2019).
cerebral edema (9 papers, 2016 to 2025). "Caveolin-1 was significantly upregulated in endothelial cells in mice with high-altitude cerebral edema." (PMID 40291503, 2025). "In hypoxic brain edema, Cav-1 forms membrane invaginations, facilitating claudin-5 endocytosis and subsequent autophagy, ultimately increasing BBB permeability and causing cerebral edema." (PMID 38922036, 2024). "To investigate the role of CAV-1 in HH-induced BBB injury and cerebral edema, we pretreated HH-treated mice with MβCD." (PMID 36253854, 2022). "Furthermore, cav-1 is shown to be upregulated following rodent cortical-cold injury and feline TBI, despite maintenance of tight junction (TJ) integrity, suggesting that physical breakdown of the barrier through loss of TJ is not necessary for the development of cerebral edema." (PMID 31333402, 2019).
diabetic nephropathy (9 papers, 2009 to 2025). "Diabetic nephropathy typically leads to endothelial cell damage, and upregulation of the Cav-1 expression." (PMID 40033218, 2025). "Regarding the remaining two genes, it has been suggested that CAV1 plays an important role in diabetic nephropathy." (PMID 34338139, 2021). "On the basis of these observations supported by the literature, we have proposed the interactions of PTPN1 with EGFR and with CAV1 as the new potential interactions in diabetic nephropathy." (PMID 19997558, 2009). "(c) The third network portrays unique interactions PTPN1 with EGFR and CAV1 which could lead to an impaired vascular function in diabetic nephropathy condition." (PMID 19997558, 2009). "Previous studies have shown that Cav-1 has antifibrotic properties by regulating cell proliferation, migration and adhesion, as well as inhibiting the TGF-β signaling pathway in diabetic kidney disease (DKD)." (PMID 34955837, 2021). "A careful modular dissection and examination of networks from diabetic nephropathy datasets exhibit the interactions between EGFR with PTPN1 and CAV1 through AKT1 activation." (PMID 19997558, 2009). "In addition to the evidence that Cav-1 expression is down-regulated by HGC in several cells, Cav-1 function has also been investigated in diabetic nephropathy, diabetic retinopathy, and diabetic wound healing." (PMID 28489581, 2017).
leukemia (9 papers, 2006 to 2024). A malignant (clonal) hematologic disorder, involving hematopoietic stem cells and characterized by the presence of primitive or atypical myeloid or lymphoid cells in the bone marrow and the blood. "The AKR/J mice develop leukemia, while the Cav1-null mice show neurodegeneration and premature aging in an early adult life." (PMID 38790233, 2024). "Caveolin-1 is expressed at high levels in leukemia cells, such as AML, CML, adult T-cell leukemia (ATL) and chronic lymphocytic leukemia (CLL) cells, compared with normal PBMCs." (PMID 35722492, 2022). "The expression of caveolin-1 in leukemia HL-60 cells can inhibit tumor cell proliferation, induce apoptosis, block PI3K/AKT signaling pathway activation and enhance chemotherapeutic agent sensitivity." (PMID 30424755, 2018). "In leukemia, CAV1 seems to be involved in the modulation of VEGF-induced redox signal transduction." (PMID 36980682, 2023). "In addition, etoposide, a therapeutic agent for leukemia, in inducing tumor cell apoptosis, increases phosphorylation of caveolin-1 Tyr14 in HL-60 cells." (PMID 17331262, 2007). "Previous studies have shown that caveolin-1 and multidrug resistance-1 (MDR-1) gene expression levels are positively correlated in relapsed leukemia." (PMID 35722492, 2022).
metastatic melanoma (9 papers, 2012 to 2023). A melanoma that has spread from its primary site to another anatomic site. "In metastatic melanoma, stromal Cav-1 loss predicted poor survival of malignant melanoma patients." (PMID 28546853, 2017). "We previously reported that Cav-1, a structural component of caveolae formation, is highly expressed in human metastatic melanoma cell lines, and is retrieved in isolated fractions of extracellular vesicles (EV)." (PMID 29783743, 2018). "Furthermore, in a phase II trial of single-agent dasatinib, five out of six metastatic melanoma patients with objective tumour-size reductions had elevated caveolin-1 expression levels before treatment." (PMID 22127285, 2012).
oral cancer (9 papers, 2005 to 2023). "Some scholars found that higher expression of miR-155, miR-21, miR-130a, CD63 and CAV1 in serum exosomes was associated with lower survival in oral cancer." (PMID 36768288, 2023). "The TT genotype of CAV1 (rs7804372) may be associated with risk for oral cancer." (PMID 34128850, 2021). "Studies on the expression of CAV1 in both cell lines and human samples of oral cancer were recently reviewed." (PMID 25633184, 2015). "Some studies reported that the expression of CAV1 increased in a stepwise manner following carcinogenesis, while others claimed that it was inactivation of CAV1 that played a role in oral cancer." (PMID 25633184, 2015). "In the context of oral cancer, the role of CAV1 in the process of EMT and/or in fibroblast-to-CAF trans-differentiation should be elucidated in further studies." (PMID 25633184, 2015). "Some studies of CAV-1 in OSCC showed an increased immunoexpression of CAV-1 in OSCC tissue when compared to normal mucosa and precancerous lesions and have shown a gradual increase of expression of CAV-1 in the different steps of cancerous process in oral cancer." (PMID 30917536, 2019). "The exosomes whose content is CAV-1, CD63, Rab5B and Annexin II are the most described in oral cancer research." (PMID 30917536, 2019). "Both in renal cell and oral carcinomas, cav-1 is overexpressed in primary tumors but low or absent in distant metastases." (PMID 15969750, 2005). "Expression of CAV1 in the TME of oral cancer has not been previously examined." (PMID 25633184, 2015). "The oral fibroblasts we describe in this manuscript, that were activated into CAFs through oral cancer cell-derived EVs, most likely constitute the CAF-S1 subtype, positive for both CD29 and FAP, while lacking expression of CAV1." (PMID 37745296, 2023). "On literature search for proteomic profiling of POSTN, TNC, CAV1 and FSCN1 in OSCC or oral cancer, we could not find any related studies reported till date." (PMID 33739025, 2021).
psoriasis (9 papers, 2013 to 2025). An autoimmune condition characterized by red, well-delineated plaques with silvery scales that are usually on the extensor surfaces and scalp. "Several skin-related disorders, especially those of the inflammatory or hyperproliferative type such as skin cancers, psoriasis, fibrosis, and wound healing, are reported to be associated with aberrant CAV-1 expression." (PMID 36532050, 2022). "In addition, Kruglikov and Scherer proved through experiments that overexpression of CAV1 can cause a reduction in psoriasis inflammation and inhibit epidermal hyperplasia, which can be used as a pathological factor and a therapeutic target for psoriasis." (PMID 35387180, 2022). "CAV1 content is downregulated in the context of various inflammatory skin conditions, including psoriasis and acne." (PMID 41516288, 2025). "Decreased CAV-1 expression in monocytes was reversed when patients were treated with anti-TNF-α antibodies, suggesting that psoriasis-related inflammatory cytokines also reduce CAV-1 expression in monocytes." (PMID 36532050, 2022). "We and others have reported that CAV-1 expression is decreased in the epidermis of patients with psoriasis." (PMID 36532050, 2022). "Imiquimod (IMQ)-induced psoriasis-like inflammation in mice showed reduced CAV-1 expression in the epidermis and monocytes, and restoration of CAV-1 function improved the severity of skin inflammation and monocyte migration into the dermis." (PMID 36532050, 2022). "Recent findings demonstrate the involvement of Cav-1 in different hyperproliferative and inflammatory skin conditions, making this protein an important pathophysiological factor in psoriasis, hypertrophic scarring, and acne." (PMID 31877626, 2019). "Because monocyte-derived macrophages serve various function, further studies are required to clarify the role of CAV-1 on monocytes/macrophages in the circumstance of psoriasis milieu." (PMID 30644419, 2019). "The levels of CAV-1 intensity in each type of cells in patients with psoriasis were lower than those in controls (reduction rate: 17 ± 10%, 16 ± 20%, and 43 ± 14% in T cells, B cells, and monocytes, respectively)." (PMID 30644419, 2019). "The present study is the first to demonstrate that CAV-1 expression is downregulated not only in keratinocytes but also in leukocytes/monocytes of patients with psoriasis and the murine model." (PMID 30644419, 2019). "We previously reported a significant reduction of CAV-1 in the epidermis of patients with psoriasis." (PMID 30644419, 2019). "In this regard, cytokine removal by biologics in patients with psoriasis resulted in increased CAV-1 level in PBMCs with clinical improvement in this study." (PMID 30644419, 2019). "We observed that CAV-1-reduced monocytes exacerbated the production of psoriasis-related inflammatory cytokines (IL-1β and IL-6)." (PMID 30644419, 2019). "CAV-1 mRNA expression in PBMCs and PMNs of patients with psoriasis was significantly reduced compared with that of healthy subjects (P = 0.022, P = 0.047, respectively)." (PMID 30644419, 2019). "CAV-1 levels in monocytes of patients with psoriasis were significantly decreased compared with those of controls (P = 0.001, P = 0.002, respectively)." (PMID 30644419, 2019). "In some patients with psoriasis who were treated with biologics, CAV-1 expression in PBMCs was serially analysed before and after treatments." (PMID 30644419, 2019). "With regard to trigger for reduced CAV-1 level, we previously proposed that psoriasis-related cytokines themselves downregulated CAV-1 expression in keratinocytes." (PMID 30644419, 2019). "We observed that CAV-1 level in psoriasis patients was apparently reduced in peripheral blood mononuclear cells (PBMCs) and it was prominent in CD14+ monocytes." (PMID 30644419, 2019). "From above, it can be proposed how spatiotemporal behavior of Cav-1 in the skin and the underlying WAT can be involved in the formation of psoriasis." (PMID 30729030, 2019).
psoriasis (continued). "First, treatment with CSD peptides ameliorated psoriasis inflammation, which was a trigger for CAV-1 downregulation." (PMID 30644419, 2019). "Whereas induced stable expression of Cav-1 improves skin appearance in psoriasis, burn wounds, and scarring, the suppression of Cav-1 can be considered as a treatment objective in aging skin." (PMID 31877626, 2019). "CAV-1 was silenced in primary human monocytes by RNA interference, and gene expression levels of psoriasis-related cytokines induced by lipopolysaccharide (LPS) were evaluated using qPCR." (PMID 30644419, 2019). "This interpretation is also consistent with the finding that caveolin-1 levels are decreased in lesional epidermis of psoriasis, a skin disease characterized by hyperproliferation of keratinocytes." (PMID 24236206, 2013). "An in vivo model also revealed the contribution of CAV-1 to the pathogenesis of psoriasis." (PMID 36532050, 2022). "Cav-1 should therefore be considered as an important target in treatment of psoriasis." (PMID 30729030, 2019). "A number of observations indicate that Cav-1 is not only a pathophysiological factor but can also serve as a target in various hyperproliferative and inflammatory skin conditions, among them in psoriasis, acne, atopic dermatitis, cutaneous fibrosis, wound healing, and skin aging." (PMID 31877626, 2019). "In this study, we hypothesized that abnormal CAV-1 level not only in keratinocytes but also in leukocytes may be involved in the pathogenesis of psoriasis." (PMID 30644419, 2019). "In summary, our study suggested that CAV-1 reduction in circulating monocytes of patients with psoriasis may play a role in the pathogenesis of psoriasis by enhancing cytokine production and promoting monocyte infiltration into the skin." (PMID 30644419, 2019). "Similarly, CAV-1 protein level in PBMCs of patients with psoriasis was significantly decreased compared with that of controls (P = 0.025)." (PMID 30644419, 2019). "Interestingly, we found an inverse correlation between CAV-1 levels in monocytes and disease duration in psoriasis patients." (PMID 30644419, 2019). "We first evaluated CAV-1 levels in leukocytes of patients with psoriasis." (PMID 30644419, 2019). "Since diminished CAV-1 level was observed not only in the epidermis but also in leukocytes of patients with psoriasis, we hypothesized that an aberrant expression of CAV-1 is present in leukocytes of this mouse model." (PMID 30644419, 2019). "Endogenous or ectopically-induced overexpression of Cav-1 in the affected skin and superficial adipose tissue reduces inflammation and suppresses epidermal hyperproliferation, thereby ameliorating these two well-known hallmarks in psoriasis." (PMID 30729030, 2019). "This study aimed to investigate whether abnormal modulation of CAV-1 on immune cells is involved in the pathogenesis of psoriasis." (PMID 30644419, 2019). "Furthermore, we observed significant CAV-1 reduction within the epidermal hyperplasia of imiquimod (IMQ)-induced murine model of psoriasis-like skin inflammation and restoration of CAV-1 function in this mice improved skin phenotype." (PMID 30644419, 2019). "Taken together, aberrant CAV-1 expression in monocytes may be involved in the pathogenesis of psoriasis." (PMID 30644419, 2019). "Low expression of caveolin-1 (Cav-1) is typical in psoriatic lesions and overexpression of Cav-1 leads to a reduction of inflammation and suppression of epidermal hyperproliferation, thus ameliorating these two well-known hallmarks of psoriasis." (PMID 30729030, 2019). "Therefore, we evaluated CAV-1 levels in leukocytes of patients with psoriasis and investigated their roles in the pathogenesis of psoriasis." (PMID 30644419, 2019). "Thus, numerous researchers have hypothesized the involvement of CAV-1 in the pathogenesis of inflammatory or hyperproliferative skin disorders, such as skin cancers, psoriasis, fibrosis, and wound healing." (PMID 36532050, 2022).